AR (androgen receptor)
Diseases named in the same sentence as AR in open-access papers (continued):
Sharing a sentence is not in itself a finding about the gene and the disease.
breast carcinoma (continued). "AR-V7 transcript was detected in all of the breast cancer cell lines except for MDA-MB-231 and CAL-51, which express the lowest levels of AR-FL." (PMID 26554309, 2015). "In our AI-resistant breast cancer model we have shown that PSAP is capable of upregulating and activating AR in the context of high HOXC11 expression." (PMID 26341737, 2015). "CYP1A1, AHR, AR, CYP1A, CYP1B1 and PTGS2 genes are common in both PCB-gene and PCB-gene-breast cancer groups." (PMID 26512648, 2015). "This cluster also contained AR and PNR, both previously shown to be co-expressed with ERα in breast cancer, as well as ERRγ." (PMID 26280373, 2015). "Recently, a large proportion of AR-positive molecular apocrine breast cancers have been shown to overexpress HER2 or PIP, an AR target gene." (PMID 25592291, 2015). "MDA-MB-453, an apocrine breast cancer cell line (ER−, PR−, HER2−, AR+) was used as a positive control and SKBR3 (ER−, PR−, HER2+, AR-low) as a negative control." (PMID 26341737, 2015). "We analyzed mRNA and protein expression data from different breast cancer cohorts for L1CAM, estrogen receptor, progesterone receptor, Her-2 and Androgen receptor (AR) and correlated the data." (PMID 25510351, 2014). "In both prostate and breast cancers high expression of FOXA1 in metastatic lesions were found, however with retained expression of AR and ERα respectively." (PMID 24849812, 2014). "While AR expression was comparable between breast cancer and normal breast tissue, PSA expression was significantly reduced (P<0.001) in breast cancer compared to normal breast samples." (PMID 25072326, 2014). "Evidence also suggests that the AR target gene, PSA, is a favorable prognostic marker in breast cancer." (PMID 25072326, 2014). "AR stimulation inhibits paracrine factors that are important for MSC interactions and breast cancer invasion and metastasis." (PMID 25072326, 2014). "Tumoral LC3A was most highly expressed in AR-negative breast cancers, while tumor BNIP3 was highest in AR-positive breast cancers." (PMID 25140630, 2014). "In addition to being a predictor of poorer response to traditional endocrine therapy and overall DFS, high levels of AR relative to ER may also identify a subset of breast cancers that would respond more favorably to enzalutamide alone or combined with tamoxifen or AIs." (PMID 24451109, 2014). "The MDA-kb-2 cell line has been developed by scientists at the EPA through a stable transfection of AR and the insertion of an MMTV-driven luciferase reporter gene into the human mammary cancer MDA-MB-453 cell line." (PMID 25111804, 2014). "While part of the correlations in Cluster 2 (HER2), Cluster 4 and Cluster 6 (ATPase activity) are preserved in ER+ breast cancer, Cluster 1 (IAC markers), Cluster 3 (AR signaling) and Cluster 5 are completely rearranged in ER+ breast cancer." (PMID 23945349, 2013). "Thus, the role of androgens or the AR in breast cancer might differ by age or menopausal status." (PMID 24403250, 2013). "We showed that in both breast cancer cell lines and tumor samples, ACSL4 expression is inversely correlated with ER and AR levels." (PMID 24155918, 2013). "Thus, AR inactivation alone does not predispose the mammary gland to mammary tumors." (PMID 23593223, 2013). "Although ERα gene amplification in breast cancers is controversial, we performed FISH analysis on tissue microarrays (TMAs) with known AR-positive breast cancers using a gene probe for AR and a centromeric chromosome X probe to query for AR gene amplification." (PMID 22321971, 2012). "To further investigate the regulation of PIP by the AR-ERK feedback loop, we used an in vivo model of molecular apocrine breast cancer." (PMID 22817771, 2012). "In addition, AR expression may also affect outcomes in given subsets of breast cancer." (PMID 22321971, 2012).
breast carcinoma (continued). "In MCF7, AR, the cognate receptor of dihydrotestosterone (DHT), an androgen that decreases the estradiol-dependent growth of breast cancer cells, was 6.8 times less expressed than ERα, whereas the difference is only 1.5 times in T47D." (PMID 22384035, 2012). "However, there are few breast cancer cell lines that express AR as the sole sex-hormone receptor, and those that do exist often harbor numerous genetic anomalies that could potentially alter AR signaling." (PMID 22321971, 2012). "To further assess the therapeutic efficacy of combined AR and MEK inhibition in molecular apocrine breast cancer, we generated xenograft tumors using MDA-MB-453 cell line." (PMID 21457548, 2011). "We have recently identified a positive feedback loop between the AR and ERK signaling pathways in molecular apocrine subtype of ER-breast cancer." (PMID 21457548, 2011). "In addition, the study aimed to elucidate whether AR diplotypes were associated with breast cancer-free survival independent of treatment, or predicted response to endocrine therapy in patients with ER-positive tumours." (PMID 22033271, 2011). "In this study, we demonstrate in vitro and in vivo synergies between AR and MEK inhibitors in molecular apocrine breast cancer." (PMID 21457548, 2011). "The expression profiles of many of the known breast cancer gene markers such as ESR1, ERBB2 and AR have been shown to follow a strong bimodal distribution, which corresponds to different tumour subtypes." (PMID 21152022, 2010). "Studies in breast carcinoma cells reveal interactions between IRS-1 and the transcription factors β-catenin, ER-α and the androgen receptor (AR)." (PMID 19534786, 2009). "Nonetheless, other cell lineage-specific transcription factors have been found amplified in cancers, including MITF in melanoma, AR in hormone-independent prostate cancer, ESR1 in breast cancer, and most recently NKX2-1 (TITF) in lung cancer." (PMID 18535672, 2008). "These stably transfected cells that overexpress the AR are derived from MCF-7 cells, an estrogen-sensitive breast cancer cell line that has been widely used in proliferation assays for testing the estrogenic potential of chemicals (E-Screen bioassay)." (PMID 18275596, 2008). "Androgen receptor (AR) signaling has emerged as a potential molecular target in triple-negative breast cancer (TNBC), a clinically aggressive and biologically heterogeneous subtype of breast cancer with limited targeted treatment options." (PMID 42121935, 2026). "Triple-negative breast cancer (TNBC) (hereafter referred to as AR + TNBC) is an aggressive breast cancer subtype that lacks the expression of estrogen receptor (ER), progesterone receptor (PR), and human epidermal growth factor receptor 2 (HER2)." (PMID 40448099, 2025). "The mechanisms of androgen receptor (AR) action in human breast cancer are complex and multifaceted, involving both genomic and non-genomic signaling pathways that influence tumor progression, metastasis, and therapeutic response." (PMID 40286049, 2025). "Although the prognostic role of AR in breast cancer is controversial, many studies have shown that the lack of AR expression is associated with an aggressive disease course and poor prognosis." (PMID 40448099, 2025). "Additionally, AR expression is often co-regulated with other factors, such as GATA-3, a transcription factor that plays a role in breast cancer differentiation and prognosis." (PMID 40286049, 2025). "We aimed to investigate the effect of AR, the AR/ER ratio, and the AR/PR ratio on CDK4/6 inhibitor treatment response in breast cancer, as well as their effects on PFS, and to validate the hypothesis that AR is a target for research." (PMID 40870508, 2025). "Additionally, beyond repressing AR and ERα activity, SAFB2 has been shown to suppress breast cancer progression by inhibiting the Wnt/β-catenin pathway via NFAT5." (PMID 40308776, 2025).
breast carcinoma (continued). "In human breast cancer, anti-androgen therapies, such as enzalutamide and bicalutamide, have shown promise in clinical trials, particularly in AR-positive, hormone receptor-negative breast cancers." (PMID 40286049, 2025). "In March 2023, the patient developed hematuria and was diagnosed with bladder metastasis based on cystoscopy and biopsy, with IHC findings indicating breast cancer origin: ER 90% (1-2+), PR <1%, HER2 (c-erbB-2) 2+, Ki-67 35%, AR 95% (3+), GATA-3+, CK (AE1/AE3)+, and P63-." (PMID 40548112, 2025). "MDA-MB-231, which does not express ERα and expresses very little AR, is the least sensitive to AA among breast cancer cells." (PMID 40940976, 2025). "In all, we demonstrate that AR promotes ER-mutant BC growth, OXPHOS, and resistance to palmitate lipotoxicity under conditions mimicking standard-of-care AI therapy under which ER-mutant metastatic breast cancer develops." (PMID 41216931, 2025). "To examine whether CRAT and AR expression are correlated in larger breast cancer datasets, we queried CRAT and AR mRNA and protein expression in the TCGA Firehose Legacy ER+ invasive breast carcinoma dataset." (PMID 41216931, 2025). "Phase II Trial (NCT02910050) combined bicalutamide with aromatase inhibitors in resistant ER+/AR+ breast cancer, showing no synergy or objective responses." (PMID 40843360, 2025). "Whilst BQ overexpression enhanced both NHEJ and homologous recombination (HR) activities, we showed that upon AR inhibition with bicalutamide (BIC), NHEJ was more significantly reduced (>50%) than HR (~50%), suggesting the dominance of NHEJ in our breast cancer model." (PMID 40940753, 2025). "Therefore, the relevance and specific regulatory mechanisms of androgen–AR signaling and CCR5–CCL5 axis in breast cancer, especially TNBC, needs to be investigated in the future." (PMID 40118451, 2025). "Long-term CDK4i treatment, commonly used for luminal A breast cancer, activates alternative pathways, such as PI3K/AKT/mTOR, androgen receptor, and Hippo signaling, along with transcriptional reprogramming via noncoding RNAs, promoting the development of drug resistance." (PMID 41161384, 2025). "Since BQ overexpression can enhance AR-signaling, we hypothesized that BQ may employ AR to induce resistance to DOX in ER+ve breast cancer by enhancing its DNA repair capacity." (PMID 40940753, 2025). "Consequently, investigating the role of ARs in canine mammary tumors could lead to a better understanding of how these tumors might respond to hormonal therapies, as well as to the development of new treatment strategies based on targeting AR signaling pathways." (PMID 40286049, 2025). "As the body of research on androgen-receptor expression in canine mammary tumors grows, it is becoming increasingly clear that ARs are not only a significant biomarker for tumor aggressiveness but are also a potentially valuable therapeutic target." (PMID 40286049, 2025). "The analysis of 19 published studies revealed AR expression in about 75% of ERα-positive breast cancer and approximately 32% of ERα-negative breast cancer." (PMID 38339092, 2024). "Indeed, our group has demonstrated that THC and CBD decrease aromatase and ERα protein levels in ER+ breast cancer cells and that CBD can also inhibit aromatase and presents ER and AR antagonistic, as well as inverse agonist, properties, in both receptors." (PMID 39338407, 2024). "Gedatolisib is currently being evaluated in a Phase 1/2 clinical trial in combination with darolutamide in patients with mCRPC previously treated with an AR inhibitor, and in a Phase 3 clinical trial in combination with palbociclib and fulvestrant in patients with HR+/HER2− advanced breast cancer." (PMID 39092562, 2024).
breast carcinoma (continued). "It is interesting to note that treating two TNBC breast cancer cell lines with a VDR agonist and an AR agonist decreased cell viability; when combined, they appeared to be additive, and viability was decreased further when the agonists were combined with chemotherapeutic drugs." (PMID 39273194, 2024). "Apocrine carcinoma of the breast (ApoCa) is a rare (∼1%), special type of breast cancer with characteristic apocrine morphology and steroid receptor expression profile: estrogen receptor (ER)-negative and androgen receptor (AR)-positive." (PMID 37782562, 2024). "The nuclear translocation of AR was observed in ERα-positive breast cancer cells but not in ERα-negative breast cancer cells." (PMID 38339092, 2024). "The androgen receptor (AR) is a tumor suppressor in estrogen receptor (ER) positive breast cancer, a role sustained in some ER negative breast cancers." (PMID 38317241, 2024). "Therefore, an important functional consequence of androgen-induced interaction between AR and GATA3 is modulation of the GATA3 cistrome to facilitate regulation of AR target genes in ER+ breast cancer cells." (PMID 38317241, 2024). "Other studies reported that THC presents anti-proliferative effects in ER+ breast cancer cells independent of ER and AR, although having the ability to impair ERα signaling by up-regulating ERβ." (PMID 39338407, 2024). "Quadruple-negative breast cancer (QNBC; ER−, PR−, HER2−, and AR−) is a highly proliferative subtype of breast cancer that has no targeted treatment options." (PMID 39335162, 2024). "To determine if a similar phenomenon occurs in the context of ER- breast cancer, we performed AR, GATA3, and H3K27ac ChIP-seq in MDA-MB-453 and MFM-223 breast cancer cell lines treated for 4 h with DHT or a vehicle control after a period of hormone deprivation." (PMID 38317241, 2024). "Molecular pathways involved in breast cancer but not in lung cancer development are androgen receptor signaling, DNA methylation, estrogen metabolism and signaling, and interleukin-10 (IL-10) anti-inflammatory signaling." (PMID 38982523, 2024). "Our discovery that AR and GATA3 cooperate to promote expression of luminal genes is consistent with molecular pathology studies reporting a strong positive correlation between AR and GATA3 expression in breast cancers, even stronger than the correlation between ER and GATA3." (PMID 38317241, 2024). "This approach revealed the DNA binding, chromatin remodeling factor GATA3 as a fundamental member of the breast cancer AR interactome regardless of disease context." (PMID 38317241, 2024). "Receiver operating characteristic curves (ROC) confirmed a significantly improved prognostic performance of PR, AR, and GATA3 expression quantified by our approach for automated breast cancer detection compared to an assessment of these markers without using the approach (each p < 0.0197)." (PMID 38137396, 2023). "In the present study, AR expression predicted a longer OS not only in HER2+ breast cancer but also in HER2+HR− nonmetastatic breast IDC." (PMID 37085500, 2023). "Because of the heterogeneity of HER2+ breast cancer and the complex mechanism of HER2 and AR, better understanding of the prognostic value of AR in all HER2+ and HER2+ hormone receptor-negative (HR−) nonmetastatic breast invasive ductal carcinoma (IDC) patients is urgent." (PMID 37085500, 2023). "We recently proposed that the mechanism present in breast cancer, where hormone-dependent estrogen receptor (ER)-mediated Hippo and YAP/TAZ regulation occurs, might be conserved in PCa via AR." (PMID 37385752, 2023). "HER2-low breast cancer is highly unstable during disease evolution and has certain biological characteristics, and breast cancer with HER2-low positivity has certain biological characteristics, which are correlated with positive HR and positive AR." (PMID 36910643, 2023).
breast carcinoma (continued). "Our study not only confirmed the prognostic role of AR in all HER2+ nonmetastatic breast IDCs but also confirmed the favorable prognostic value of AR in HER2+HR− nonmetastatic breast cancers." (PMID 37085500, 2023). "In the TNBC cohort (n=73), the AR positive rate was 31.5%, and the incidence of HER2-low was higher in AR positive breast cancer than in AR negative (86.96% VS 52.00%)." (PMID 36910643, 2023). "AR signaling is suggested to have immunomodulatory functions in some malignancies, including breast cancer; however, its immunological role in breast cancer has not been fully validated." (PMID 36721218, 2023). "The status of ER, PgR, AR, PD-L1 (hPD-L1), and TIL (hTIL) in breast cancer tissue was histologically evaluated by IHC and H&E staining using the samples obtained at our facility from 45 patients with breast cancer." (PMID 36721218, 2023). "While AR expression by IHC is the gold standard, previous studies have also investigated mRNA expression of AR in primary breast cancer, although to our knowledge there have been no such studies in breast cancer BrM." (PMID 37345085, 2023). "Finally, there is preclinical data to support AR activation as a therapeutic strategy for ER + breast cancer, including ET and CDK4/6 inhibitor resistant ER + breast cancer models." (PMID 37035239, 2023). "AR signaling also promotes proliferation in ER-negative, HER2-positive breast cancer." (PMID 37681860, 2023). "AR expression is a common feature of both invasive and noninvasive breast cancer, especially in HR− breast cancer." (PMID 37237509, 2023). "Herein, we analyzed KIFC1 RNA levels and their associations with clinical features and outcomes among AR-low and AR-high TNBC tumors in three distinct publicly available gene expression datasets and in the breast cancer gene expression database (bc-GenExMiner)." (PMID 38003261, 2023). "Moreover, the studies on male breast cancers with an extra X-chromosome revealed the hypomethylation of the AR gene together with the CTA MAGEA family members, the coregulators of AR, both mapped on the X-chromosome’s q-arm." (PMID 37511419, 2023). "We explored the association between AR and immune infiltration in HER2+ nonmetastatic breast cancer to deepen the current understanding of this disease, increase the stratification of prognosis and hope to facilitate individualized treatment." (PMID 37085500, 2023). "FOXA demonstrates a crucial role in the synchronization of estrogen-receptor and androgen-receptor functions, so it is not as startling to discover the presence of forkhead-box A gene expression in ER-positive breast cancer and AR-positive prostate tumors." (PMID 37626655, 2023). "AR+ status was markedly related to better OS in HER2+HR− nonmetastatic breast cancer patients, while a negative correlation was observed between AR and PD-L1/TILs." (PMID 37085500, 2023). "To confirm whether ASR-600 affects other pro-survival signaling pathways apart from AR in CRPC, we examined AKT, mTOR, Estrogen receptor (ER), and Progesterone receptor (PR) expressions in prostate and breast cancer cell lines." (PMID 36937838, 2023). "This cohort contained a subset of genes that could be considered potential biomarkers for breast cancer progression, including FOXA1, MLPH, ESR1, AR, GATA3, TFF1, THSD4, and TBC1D9." (PMID 38020889, 2023). "AR-negative, EGFR-positive breast TNBC breast cancer patients constitute the high-risk group, with highly proliferative tumors and consistently worse patient outcomes." (PMID 38203649, 2023). "Epidemiological evidence suggests that among HER2+ER− patients with nonmetastatic breast cancer, AR+ patients seem to have a worse prognosis." (PMID 37085500, 2023). "Despite the tumor suppressive effect of AR in ER+ breast cancer, bicalutamide and enzalutamide have shown potent clinical anti‐cancer activities in AR+ triple‐negative breast cancer (TNBC)." (PMID 37092583, 2023).